HSPA6 (heat shock protein family A (Hsp70) member 6)
Description:
Molecular chaperone implicated in a wide variety of cellular processes, including protection of the proteome from stress, folding and transport of newly synthesized polypeptides, activation of proteolysis of misfolded proteins and the formation and dissociation of protein complexes. Plays a pivotal role in the protein quality control system, ensuring the correct folding of proteins, the re-folding of misfolded proteins and controlling the targeting of proteins for subsequent degradation. This is achieved through cycles of ATP binding, ATP hydrolysis and ADP release, mediated by co-chaperones. The affinity for polypeptides is regulated by its nucleotide bound state. In the ATP-bound form, it has a low affinity for substrate proteins. However, upon hydrolysis of the ATP to ADP, it undergoes a conformational change that increases its affinity for substrate proteins. It goes through repeated cycles of ATP hydrolysis and nucleotide exchange, which permits cycles of substrate binding and release.
Synonyms: HSP70B'
Tractability: Small molecule: a structure with a bound ligand is known. Antibody: its Gene Ontology location is reachable by antibodies, with high confidence. PROTAC: ubiquitination databases record sites on it.
Target class: Other cytosolic protein
Gene: Protein-coding gene on chromosome 1 (161,524,540 to 161,526,894, forward strand). Ensembl gene ENSG00000173110.
Subcellular location (Human Protein Atlas): Annulus; Flagellar centriole; Vesicles; Calyx; Perinuclear theca
Pathways (Reactome):
Cellular responses to stimuli: Attenuation phase; HSF1 activation; HSF1-dependent transactivation; Regulation of HSF1-mediated heat shock response
Immune System: Neutrophil degranulation
Gene Ontology:
Molecular function: ATP hydrolysis activity; enzyme binding; heat shock protein binding; protein binding; protein folding chaperone; ATP binding
Biological process: cellular heat acclimation; cellular response to heat; protein refolding; response to unfolded protein
Cellular component: blood microparticle; centriole; COP9 signalosome; cytoplasm; cytosol; extracellular exosome; extracellular region; ficolin-1-rich granule lumen; nucleus; plasma membrane; secretory granule lumen
Genetic constraint (gnomAD): Loss-of-function variants: 0 observed, 0.16 expected, observed/expected ratio (o/e) 0, 90% interval 0 to 1.88. That is too few expected variants to judge how well the gene tolerates losing a copy. Missense variants: 696 observed, 785.43 expected, observed/expected ratio (o/e) 0.89, 90% interval 0.83 to 0.94. Synonymous variants: 301 observed, 330.69 expected, observed/expected ratio (o/e) 0.91, 90% interval 0.83 to 1.
Homologues: Orthologues: pig HSPA6 (95% identical), guinea pig HSPA6 (93% identical), Caenorhabditis elegans F44E5.4 (68% identical), Caenorhabditis elegans F44E5.5 (68% identical), Caenorhabditis elegans hsp-70 (67% identical), Drosophila melanogaster Hsp110 (29% identical), Caenorhabditis elegans hsp-110 (29% identical). Paralogues in human: HSPA1A (81% identical), HSPA1B (81% identical), HSPA1L (79% identical), HSPA8 (78% identical), HSPA2 (78% identical), HSPA5 (61% identical), HSPA9 (51% identical), HSPA4 (35% identical), HSPA4L (32% identical), HSPH1 (32% identical), HYOU1 (32% identical), HSPA14 (28% identical), and 1 more.
Diseases named in the same sentence as HSPA6 in open-access papers:
HSPA6 is named in the same sentence as 69 diseases in open-access papers, as found by Europe PMC text mining. Sharing a sentence is not in itself a finding about the gene and the disease. The quoted sentences say what the papers report.
breast carcinoma (12 papers, 2014 to 2025). "Studies have also indicated that HSPA6 expression is increased in hepatocellular carcinoma and breast cancer and that HSPA6 expression is associated with the early recurrence of hepatocellular carcinoma." (PMID 40765077, 2025). "Surprisingly, the overexpression of one of the inducible HSP70 forms, HSPA6, in breast cancer cells may somehow be associated with the repression of their malignant traits." (PMID 34943954, 2021). "The analysis of the Oncomine database showed that HSPA6 is overexpressed in breast cancer, CNS, and brain malignancies, cervical cancer, kidney cancer, lymphoma and leukemia, and GC and colorectal cancer." (PMID 41244835, 2025). "The high expression of HSPA6 is positively correlated with the overall survival of breast cancer patients, suggesting that HSPA6 has a tumour suppressor effect." (PMID 39716349, 2025). "Screening of the Oncomine database revealed that HSPA6 is overexpressed in kidney cancer, brain and CNS cancers, leukemia and lymphoma, breast cancer, cervical cancer, colorectal cancer and GC." (PMID 36458368, 2023). "Recently, HSPA6 was found to be indispensable in the Withaferin A-mediated inhibition of apoptosis/autophagy or migration in breast cancer cells." (PMID 37063290, 2023). "Altogether, identification of TQ-targeted HSPA6 not only reveals a new TQ regulatory mechanism, but also provides a novel candidate target for clinical management and treatment of breast cancer, particularly for TNBC upon TQ." (PMID 34017687, 2021). "Recently, HSPA6 was discovered to be dispensable for Withaferin A-mediated apoptosis/autophagy or migration inhibition of breast cancer." (PMID 34017687, 2021). "Altogether, identification of HSPA6 will provide a novel candidate target for clinical management and treatment of breast cancer, particularly for TNBC on TQ." (PMID 34017687, 2021). "High expression of HSPA6 was positively correlated with long overall survival (OS) in patients with breast cancer, indicating the tumor-suppressive roles for HSPA6." (PMID 34017687, 2021). "This intriguing publication needs, though, confirmation, while the implication of HSPA6 in the breast cancer pathogenesis remains to be established." (PMID 34943954, 2021). "HSPA6 showed moderate expression in lung cancer, breast cancer, endometrial cancer, ovarian cancer and melanoma and negative expression in endometrial cancer, renal cancer and liver cancer." (PMID 34712697, 2021). "The regulatory mechanisms and prognosis for HSPA6 for breast cancer survival were conducted through bioinformatics and online databases." (PMID 34017687, 2021). "HSPA6 mRNA was up-regulated in breast cancer, kidney renal clear cell carcinoma and kidney renal papillary cell carcinoma." (PMID 34712697, 2021). "It has been reported that TQ inhibits breast cancer cell migration and invasion, and further study here reveals that TQ upregulates HSPA6 expression." (PMID 34017687, 2021). "Through analyzing the clinical data of breast cancer by Kaplan-Meier Plotter, we found that high expression of HSPA6 was positively correlated with long OS in patients with both all subtypes of breast cancer and TNBC, indicating the tumor-suppressive roles for HSPA6." (PMID 34017687, 2021). "Nevertheless HSPA6 can serve as a prognostic marker for breast cancer." (PMID 34017687, 2021). "Thus, the data through bioinformatics analysis of multiple databases support the inhibitory effect of HSPA6 on breast cancer." (PMID 34017687, 2021). "Therefore, identification of HSPA6 not only reveals a new TQ regulatory mechanism, but also provides a novel candidate gene for clinical management and treatment of breast cancer, particularly for TNBC." (PMID 34017687, 2021). "Apparently, HSP1A and HSPA8 are expressed in all breast cancer subtypes; HSPA2 is higher in luminal, while HSPA5 and HSPA6 are higher in basal subtypes." (PMID 34943954, 2021).
breast carcinoma (continued). "A similar response of HSF1 to MA that was accompanied by overproduction of HSPA1 and HSPA6 expression and HSPA2 downregulation was also observed in the wild type (wt) MCF7 breast cancer cell line." (PMID 34200371, 2021). "It was found that HSPA6 is not necessary for withaferin A-mediated suppression of breast cancer migration or apoptosis/autophagy." (PMID 41244835, 2025). "It has been reported that HSPA6 has an inhibitory effect on the growth, migration, and invasion of three negative breast cancer cells." (PMID 39716349, 2025). "To further investigate the HSPA6 expressions and its clinical significance in breast cancer patients, we thus utilized the data from CPTAC, and results showed that the HSPA6 protein expressions were decreased in breast cancer tissues compared with normal tissues." (PMID 34017687, 2021). "TQ has been reported to inhibit breast cancer cell migration and invasion and epithelial-mesenchymal transition (EMT) markers, and our RNA-seq data further revealed that TQ upregulates HSPA6 expression." (PMID 34017687, 2021). "But DNA methylation of HSPA6 may not be the regulatory mechanism for HSPA6 mRNA upregulation in breast cancer tissues, although the mRNA levels of HSPA6 were increased in these cancer tissues compared with normal tissues." (PMID 34017687, 2021). "However, the mRNA levels of HSPA6 were increased in breast cancer tissues compared with normal tissues (data not shown)." (PMID 34017687, 2021). "MCF10A cells exhibited significantly increased expression of HSP90AA1, CARHSP1, HSPA12A and decreased expression of HSPB1, HSPBL2, HSPA6, and HSPA7 (C vs H), while the three breast cancer lines showed no significant 2-fold or greater alterations in the expression of these genes (C’ vs H’)." (PMID 24511912, 2014).
bladder cancer (10 papers, 2016 to 2025). "HSPA6 enhanced the inhibitory effect of garlic extract on the proliferation, migration, and invasion of bladder cancer EJ cells." (PMID 36035171, 2022). "Overexpression of the HSPA6 gene was related to the proliferation, migration, and invasiveness of bladder cancer cells." (PMID 33833821, 2021). "HSPA6 was also reported to inhibit the proliferation and invasion of garlic extract-treated bladder cancer cells." (PMID 32947888, 2020). "Further study is necessary to examine the combinational anti-tumor efficacy of HSPA6 gene and GE using a bladder cancer-derived xenograft animal model." (PMID 28187175, 2017). "Furthermore, one study found that HSPA6 enhances the inhibitory effects of garlic extract on the proliferation, migration and invasion of bladder cancer cells." (PMID 40765077, 2025). "Other studies indicated that HSPA6 may have an inhibitory effect on bladder cancer, lung cancer, and triple-negative breast cancer, while may be relevant to the early recurrence of human hepatocellular carcinoma." (PMID 35281087, 2022). "Recent studies have found that HSPA6 can enhance the inhibitory effect of garlic extract on the proliferation, migration, and invasion of bladder cancer cells by enhancing the ATM-CHK2-Cdc25C-p21 WAF1-Cdc2 cascade response and MAPK and Akt phosphorylation and inhibiting MMP-9 expression." (PMID 34489426, 2021). "However, in a recent study, HSPA6 expression was correlated with the inhibition of proliferation, migration and invasion, thereby enhancing the anti-tumor effect of garlic extract in bladder cancer." (PMID 31370342, 2019). "However, in disagreement with previous results, our data showed that HSPA6 enhanced GE-induced inhibition of cellular physiology, including proliferation, migration, and invasion, in bladder cancer EJ cells." (PMID 28187175, 2017).
triple-negative breast carcinoma (7 papers, 2021 to 2025). An invasive breast carcinoma which is negative for expression of estrogen receptor (ER), progesterone receptor (PR), and human epidermal growth factor receptor 2 (HER2). "The invasion, migration, and growth of cells in triple-negative breast cancer were decreased by overexpression of HSPA6." (PMID 41244835, 2025). "RNA sequencing revealed that heat shock 70-kDa protein 6 (HSPA6), a novel thymoquinone upregulation gene, inhibited the growth, migration, and invasion of triple-negative breast cancer cells." (PMID 36035171, 2022). "In turn, thymoquinone deserves attention as a natural compound, potentially having HSPA6-dependent activities against triple negative breast cancer." (PMID 34943954, 2021). "Knocking down HSPA6 promoted triple-negative breast cancer cell growth, migration, and invasion." (PMID 36927457, 2023). "By using RNA sequencing, it was possible to identify HSPA6, the TQ-targeted gene, for functional TNBC (triple-negative breast cancer) inhibition." (PMID 41244835, 2025).
lung carcinoma (6 papers, 2016 to 2025). "The expression of HSPA6 were found associated with the lung cancer, leukemia and baldder cancer’s migration, invasion and proliferation." (PMID 34412642, 2021). "Numerous investigations have shown that HSPA6 plays an important role in multiple human cancers, including esophageal cancer, glioma, lung cancer, hepatocellular carcinoma and leukemia." (PMID 34412642, 2021). "The present study proposed the HSPA6‐dominated transcriptional signals as the part of molecular mechanisms of lung cancer cell sensitivity to acRoots on the basis of acRoots‐altered profiles of transcriptional factors." (PMID 32508044, 2020). "Furthermore, we evaluated the decisive role of HSPA6 in the sensitivity of lung cancer cell to acRoots treatment by monitoring the balance of cell proliferation and apoptosis of acRoots‐sensitive and less‐sensitive lung cancer cells with or without HSPA gene." (PMID 32508044, 2020). "The HSPA6 gene is potentially to be a combined drug therapy target in lung cancer." (PMID 32508044, 2020). "Besides, treating lung cancer cells with Manumycin A induced up-regulation of HSPA6, which could form a positive feedback loop and sensitize cancer cells to Manumycin A treatment." (PMID 36597133, 2023). "HSPA6 has been identified as a crucial regulator of cell sensitivity, likely through its interactions with other members of the HSPA family during lung cancer progression." (PMID 40796704, 2025). "Of those identified target genes, we selected HSPA6, histidine‐rich glycoprotein (HRG), ubiquitin D, prostaglandin E synthase (PTGES), tyrosine kinase (TXK), and MMP2 and measured those gene expressions in eight lung cancer cells 48 h after treatment with acRoots at 10 mg/mL." (PMID 32508044, 2020).
gastric cancer (5 papers, 2021 to 2025). A primary or metastatic malignant neoplasm involving the stomach. "Overexpression of TRIM22 significantly inhibited the proliferation, colony formation, and migration of gastric cancer cells and downregulated the expression of HSPA6." (PMID 34489426, 2021). "HSPA6 enhances gastric cancer cell proliferation by increasing cyclinB1 and YAP levels." (PMID 40313859, 2025). "This study aimed to explore the clinical relevance of heat shock protein family A member 6 (HSPA6) in gastric cancer (GC) and its effect on GC cell proliferation." (PMID 36458368, 2023).
hepatocellular carcinoma (5 papers, 2017 to 2025). A malignant tumor that arises from hepatocytes. "HSPA6 in upregulated in hepatocellular carcinoma and breast and is associated with poor outcomes in hepatocellular carcinoma." (PMID 29029430, 2017). "HSP90B1 is proposed to be associated with poor survival from hepatocellular carcinoma (HCC), whereas high levels of HSPA5 and HSPA6 may be associated with earlier recurrence of HCC." (PMID 31101113, 2019).
glioma (4 papers, 2022 to 2024). A benign or malignant brain and spinal cord tumor that arises from glial cells (astrocytes, oligodendrocytes, ependymal cells). "The association between HSPA6 expression and relevant clinical factors in patients with glioma further indicated that there were significant differences in certain clinical traits, including IDH, 1p/19q, grade, and age." (PMID 35281087, 2022). "Our results showed that various types of immune-associated cells had been produced in patients with glioma and that most of the immune checkpoints were significantly higher in the subgroup of patients with high expression levels of HSPA6." (PMID 35281087, 2022). "Finally, three of the six types of TIIC were found to be associated with HSPA6 CNV in patients with low grade gliomas (LGGs) and glioblastoma (GBM)." (PMID 35281087, 2022). "In addition, we conducted GSVA to investigate the potential pathways associated with the low and high subgroups of HSPA6 expression in patients with gliomas." (PMID 35281087, 2022). "Moreover, Univariate and multivariate Cox regression analyses displayed that HSPA6 was meaningfully statistical significance (p < 0.05) which was associated with clinical outcome in patients with gliomas in the three cohorts." (PMID 35281087, 2022). "To further investigate the mechanisms undergoing how HSPA6 may be associated with the outcome of patients with glioma, we identified DEGs by comparing subgroups with low and high expression levels of HSPA6 in the three cohorts (FDR <0.05 and log2Fold Change >1) using the Wilcoxon rank sum test." (PMID 35281087, 2022). "Although the role of HSPA6 in cancer progression needs to be clarified, its expression was previously correlated with malignant progression in glioma." (PMID 37623854, 2023). "Although the role of HSPA6 in cancer progression needs to be clarified, its expression has been shown to correlate with malignant progression in gliomas." (PMID 37623854, 2023). "Collectively, these results implied that patients with gliomas with high expression levels of HSPA6 exhibited a special immunological reaction." (PMID 35281087, 2022). "Next, we further verified the relationship between HSPA6 and the malignant progression of glioma cell lines in vitro." (PMID 35281087, 2022). "To further verify the association between HSPA6 expression and the malignant progression of glioma, we inspected the differential expression of HSPA6 in these glioma cell lines." (PMID 35281087, 2022). "This led to the question as to what controls the expression of HSPA6 protein in patients with glioma." (PMID 35281087, 2022). "Next, a range of functional experiments were undertaken to investigate the connection between HSPA6 expression and the degree of malignancy in glioma cells from different treatment groups." (PMID 35281087, 2022). "Compared with para-carcinoma tissues, HSPA6 protein was highly expressed in clinical samples of glioma." (PMID 35281087, 2022). "We also verified that HSPA6 protein was expressed at significantly higher levels in clinical glioma specimens than in matched para-cancerous tissues." (PMID 35281087, 2022). "The expression levels of HSPA6 proteins were much higher in the glioma tissues compared with matched para-cancerous tissue." (PMID 35281087, 2022). "Vitro experiments further verified that HSPA6 enhanced the malignant progression of glioma cells by promoting proliferation, invasion and anti-apoptosis." (PMID 35281087, 2022). "Patients with gliomas were split into low and high subgroups based on their median expression level of HSPA6 in the TCGA." (PMID 35281087, 2022). "Next, we investigated the differences in expression of diverse immune checkpoints between the subgroups of glioma patients with low and high HSPA6 expression." (PMID 35281087, 2022). "Herein, we described the biological functionality of HSPA6 in patients with glioma for the first time and verified our findings by performing in vitro experiments." (PMID 35281087, 2022).